EZH2 (enhancer of zeste 2 polycomb repressive complex 2 subunit)
Diseases named in the same sentence as EZH2 in open-access papers (continued):
Sharing a sentence is not in itself a finding about the gene and the disease.
tumor (continued). "Similarly, TNK2-AS1 can bind to EZH2 and silence CUGBP Elav-like family member 2 (CELF2), with these processes subsequently activating the PI3K/Akt pathway in AML cells to promote tumor development." (PMID 39655332, 2024). "The modest response to EZH2 inhibition was validated in vivo using an NEPC patient-derived xenograft (PDX) model (WCM12) where we found that the tumor growth rate was not significantly impacted when treated with tazemetostat compared to vehicle." (PMID 38405800, 2024). "Furthermore, we demonstrate strong tumor control in models of both autochthonous and syngeneic LSCC treated with anti-PD1 immunotherapy with EZH2 inhibition." (PMID 38265267, 2024). "While our findings support a tumor-suppressive role in restricting PanIN and PDAC formation, future studies are needed to determine if these effects are simply due to PRC2-related functions or additional modes of EZH2 activity." (PMID 39739419, 2024). "Targeted inhibition of DNMT, EZH2, HDACs, and lysine-specific demethylase 1 (LSD1) has been shown to induce the expression of chemokines resulting in increased T cell infiltration into the tumor microenvironment and enhanced antitumor immunity." (PMID 38665224, 2024). "Beyond EZH2 inhibitors, novel agents are being developed to target non-histone PTMs, which also play critical roles in tumor progression, especially in CNS tumors." (PMID 39456545, 2024). "EZH2 is the catalytic subunit of polycomb repressive complex 2 (PRC2), which has histone methyltransferase activity and can catalyse the methylation of lysine 27 of histone H3 (H3K27) to regulate the expression of tumour suppressor genes." (PMID 38644473, 2024). "Additionally, NEAT1 has been shown to recruit and directly bind to EZH2, a functional part of an epigenetic regulatory complex polycomb repressive complex 2 (PRC2), which promotes tumor cell proliferation and invasion." (PMID 38646788, 2024). "The analyzed data indicates that EZH2 expression intensity does not increase exponentially in tumor tissue, but is altered during tumor progression, and outcome parameters should be evaluated individually." (PMID 40135141, 2024). "Thus, combining EZH2 inhibition with immunotherapy improves T-cell infiltration, promoting IFN-γ-producing CD8+ T cells in the TME and enhancing tumor control." (PMID 38534385, 2024). "While the opposite was observed in tumor cells, with PRC2 up-regulation leading to down-regulation of PD-L1, it is interesting to see that anti-CLTA-4 immune checkpoint inhibitor therapy is actually improved when given in conjunction with EZH2 therapies." (PMID 39689157, 2024). "EZH2 expression has been found to catalyze histone H3K27 trimethylation (H3K27me3) at the promoter of the epithelial gene E-cadherin, leading to silencing of E-cadherin, which promotes cellular EMT development and tumor invasion." (PMID 39013911, 2024). "Notably, miR-let-7 is one such miRNA that not only inhibits EZH2 but targets oncogenes like MYC and K-RAS, enhancing its tumor-suppressive properties." (PMID 39055532, 2024). "Inhibition or knockdown of EZH2 and KDM1A may therefore suppress tumour formation, as well as therapies that target dysregulated pathways that are related to frequently mutated epigenetic modifiers." (PMID 39624739, 2024). "Compared to normal hepatocytes from control tissue, the tumor cells were positive for nuclear AR (androgen receptor) expression but had no increased EZH2 (Enhancer of Zeste 2 Polycomb Repressive Complex 2 Subunit) protein expression." (PMID 39061609, 2024). "Specifically, the EZH2 inhibitor GSK126 decreases DMG cell proliferation in vitro and may be combined with statins to inhibit tumor growth in in vivo models of DMG." (PMID 38994974, 2024). "In addition, reports have shown that GAS5 interacts with some proteins, such as E2F1, E2F4, YBX1, EZH2, and YAP, which inhibit tumor progression." (PMID 38782769, 2024).
tumor (continued). "Furthermore, SOX4 promotes TMZ resistance in GBM by interacting with EZH2 and coactivating METTL3, resulting in transcriptional plasticity of tumor cells." (PMID 38331879, 2024). "Thus, we next moved to test the impacts of EZH2 knockout and overexpression on 4T1 TNBC primary tumor growth and metastasis in vivo." (PMID 38791429, 2024). "DYB‐03 showed promising antitumor activity in a xenograft tumor model by promoting apoptosis and inhibiting angiogenesis, which could be almost abolished by the deletion of HIF‐1α and EZH2." (PMID 38072662, 2024). "However, the role of EZH2 in AML can be context-dependent, as it has been shown to function as an oncogene during AML development and a tumor suppressor during the AML maintenance phase." (PMID 38339323, 2024). "Hence, MELK silencing downregulated EZH2 to inhibit LUAD cell proliferation and invasion and induce apoptosis, thereby suppressing tumour growth." (PMID 38652219, 2024). "Second, this study revealed significant effects of tumor-intrinsic EZH2 knockout on TIN/TIL poise, but did not provide functional and/or signaling data on these tumor-associated immune cells." (PMID 38791429, 2024). "Our in vivo experiments using the STING agonist MSA-2 as a longitudinal treatment combined with either 4T1 WT or EZH2 KO cells showed significant reductions in primary tumor growth and metastasis potential for the former, but not the latter." (PMID 38791429, 2024). "Small molecule EZH2 inhibition can simultaneously up-regulate NKG2D ligand on tumor cells, indicating that EZH2i can enhance NK killing by simultaneously regulating important NK activation molecules on NK cells and tumor cells." (PMID 38665224, 2024). "Specifically, the study aimed to assess how DNMT1 and DNMT3A, influenced by EZH2, affect the methylation and expression levels of miR-570-3p, and to determine the impact of estradiol (E2) on these processes and the subsequent effects on PTC tumor growth." (PMID 38890707, 2024). "Furthermore, the administration of the shRNA SIRT7 and shRNA EZH2 lentiviruses, along with CDDP, resulted in the most pronounced tumor growth inhibition effect in mice." (PMID 39719443, 2024). "In clear cell renal cell carcinoma (ccRCC) and TNBC, hypoxia and HIF-1α play a pivotal role in amplifying the metastatic potential of tumor cells through non-canonical functions and enhanced EZH2 phosphorylation." (PMID 38911968, 2024). "Impaired histone methyltransferase, enhancer of zeste homolog 2 (EZH2), can be recruited to solute carrier family 16 member 9 (SLC16A9), a carnitine transporter, coordinated by the direct interaction of PKM2, thus epigenetically influencing tumor progression." (PMID 39484162, 2024). "Notably, dual EZH2/CDK4/6 blockade also reduced 3D-spheroid invasion, partially inhibited tumor growth in ovo, and led to impaired viability of patient-derived organoids." (PMID 39054369, 2024). "Inhibiting enzymes like EZH2 can reactivate tumor suppressor genes, as demonstrated by tazemetostat, while BET protein inhibitors such as JQ1 and CPI-0610 modulate immune checkpoint molecules, reducing tumor-induced immunosuppression." (PMID 39483548, 2024). "Enhancer of Zeste Homolog 2 (EZH2) is a histone methyltransferase and a critical epigenetic regulator in many malignancies that primarily functions as an epigenetic silencer and is involved in the methylation of more than 200 tumor suppressor genes." (PMID 39409893, 2024). "In the study of EZH2 on tumor therapy, our study suggests that specific inhibitors that can reduce its TRM-inhibitory effect should be further developed, or act precisely on tumor through targeted delivery systems such as nanomaterials." (PMID 38243324, 2024). "Furthermore, the binding of EZH2 and H3K27me3 to the promoter of APC leads to its inhibition, thereby contributing to the accumulation of tumor stem cells and the development of chemotherapy resistance." (PMID 38600608, 2024).
tumor (continued). "This study proposed a role for EZH2 in NFATc1 regulation and PDAC progression, suggesting that EZH2’s role may extend to the tumor microenvironment." (PMID 39739419, 2024). "This study, focusing on EZH2, an important epigenetic regulator, and associated intracellular signaling molecules, demonstrates that both EZH2 and pERK expression are upregulated in ATLL, contributing to tumor aggressiveness in biopsied patients’ tumor tissues." (PMID 38339397, 2024). "Subsequently, we leveraged proteomic data from the CPTAC database to validate EZH2 expression at the protein level, finding marked overexpression of the EZH2 protein in LIHC tumor tissues, though not in KIRC." (PMID 39516467, 2024). "Furthermore, the knockdown of UCA1 in gastric cancer cells enhanced cisplatin-induced apoptosis, possibly through its reduced ability to recruit EZH2 and to activate the PI3K/AKT signaling pathway, which is involved in tumor progression." (PMID 38256203, 2024). "One important limitation of this study is the correlative nature of our in vivo experiments that do not separate tumor cell-intrinsic from immune cell–dependent mechanism of EZH2 inhibition." (PMID 38265267, 2024). "EZH2 expression was not correlated with histological grade, primary tumor status, or the presence of nodal metastasis." (PMID 38791289, 2024). "Notwithstanding the absence of a correlation between the extent of EZH2 expression and clinical parameters under consideration, it is evident that the majority of the evaluated cSCC tumor tissue samples exhibited EZH2 expression." (PMID 40135141, 2024). "The combined inhibition of EZH2 and DOT1L HMTs using the small molecule inhibitors GSK343 and SGC0946, respectively, resulted in synergistic cell death in vitro as well as modest anti‐tumour efficacy in vivo." (PMID 39501501, 2024). "Overexpression of EZH2 in LC cells promotes the production of tumor-derived CCL5, leading to recruitment of M2-like macrophages and immunosuppressive Treg cells, which can facilitate tumor proliferation and metastasis while inhibiting CD8+ T cells." (PMID 37909018, 2023). "Depletion of Ezh2 was correlated with disruption of CD8+ Teff cell differentiation, suggesting synergistic regulation between epigenetic modification, antitumor immunity, and tumor signaling pathways." (PMID 37330579, 2023). "Treatment with EZH2 and DNMT1 epigenetic regulators synergistically loosened Th1‐type chemokine repression and promoted effector T‐cell tumor trafficking; thus, ultimately potentiating the therapeutic effect of programmed death‐ligand 1 (PD‐L1) and adoptive T‐cell transfusion." (PMID 36599655, 2023). "Enhancer of Zeste Homolog 2 (EZH2) is a core component of Polycomb Repressive Complex 2 (PRC2), which has been reported to play important role in oncogenesis, tumour growth and metastasis in numerous malignant tumours by regulating gene expression through trimethylation of H3K27." (PMID 37202806, 2023). "As previously discussed, activation of the JAK/STAT pathway in ENKTL converts the histone methyltransferase EZH2 into a non-canonical transcriptional activator of genes involved in cell proliferation, with inhibition of JAK3 decreasing EZH2 expression and decreasing ENKTL tumor growth." (PMID 36900160, 2023). "Notably, EZH2-mutant DLBCL exhibited similar sensitivity to VTP50469 as EZH2i and combination therapy substantially enhanced tumour killing." (PMID 36635503, 2023). "In fusion negative (FNRMS) tumours, EZH2 overexpression sustained proliferation, and EZH2 inhibition lead to myogenic differentiation." (PMID 37858275, 2023). "We verified the expression of EZH2 in 24 pairs of HBV-related HCC tumor tissues compared to normal adjacent liver tissue." (PMID 37689710, 2023). "EZH2 was found to regulate the proliferation of HCC cells and promote HCC progression in a variety of ways, for example, previous studies have shown that CHD5 is a tumor suppressor." (PMID 37268997, 2023).
tumor (continued). "Independent of its H3K27 trimethylation activity, tumour proliferation is also correlated with the entire EZH2 protein." (PMID 37667522, 2023). "Therefore, the inhibition of EZH2 leads to HCC cell eradication via NKs by upregulating expression of ULBP3 and ULBP4 in tumor cells." (PMID 37928272, 2023). "Of note, EZH2 overexpression may directly modulate the process of epithelial-mesenchymal transition (EMT) and therefore affect tumor cell migration and invasion." (PMID 38031139, 2023). "EZH2 inhibitors up-regulate the permeability of immune cells in tumor microenvironment and induce reprogramming of immunosuppressive cells, thus enhancing the killing effect of PARP inhibitors on tumor cells." (PMID 36611214, 2023). "Notably, MALAT1 recruits EZH2 (Enhancer of zeste homolog 2) and increases H3K27 trimethylation level at target loci to inhibit gene expression, thereby facilitates tumor malignancy." (PMID 36813772, 2023). "A total of 103 samples from 20 PCa patients were analyzed; foci of adjacent non‐tumor prostate tissue, HGPIN, GL3, GL4, GL5, and LN were examined to determine the presence of the TMPRSS2‐ERG fusion and ERG, EZH2, NKX3.1, and SPINK‐1 expression levels, using RT‐PCR." (PMID 36199157, 2023). "In addition, epigenetic alterations, including the overexpression of epigenetic modulators such as EZH2 and SOX2, seem to be involved in tumor evolution as components of lineage plasticity." (PMID 37686633, 2023). "Their results showed that EZH2 mRNA (p < .0001) and protein expression (p < .0001) in tumor specimens were significantly higher than in the matched-normal tissue." (PMID 38146588, 2023). "Besides, the expression of 7 genes (EZH2, FLT1, IRS1, KDR2, MYB2, JUN, and TIMP2) was significantly different in metastatic tissue when compared with the primary tumor." (PMID 36879084, 2023). "We found that EZH2 was expressed in the nuclei of tumor cells, but not in normal pancreatic tissues." (PMID 37198697, 2023). "Notably, Akt/NICD1/Control (A/N+C) mice showed a large tumour load in the liver, while Akt/NICD1/ Ezh2 knockdown (A/N+shEzh2#1, A/N+shEzh2#2) mice showed only a few small lesions in the liver after 5 weeks of plasmid injection." (PMID 38050190, 2023). "Furthermore, the combination of EZH2 inhibitor and TIGIT monoclonal antibody blockade enhanced the anti-tumor effect of natural killer cells." (PMID 37239949, 2023). "Moreover, expression of EZH2 and TOP2A is significantly correlated with tumor differentiation grade, tumor invasion, and TNM stage in HCC." (PMID 38008711, 2023). "In 2022, researchers demonstrated that inhibition of EZH2 and HDAC could reactivate IFI16-directed immune response of HER2-positive BC patients, changing “cold tumor” into “hot tumor”, and sensitizing anti-HER2 treatment responses." (PMID 37803297, 2023). "Tazemetostat (EPZ6438) is an FDA-approved drug with high selectivity towards EZH2, which demonstrates a significant reduction in tumor weight in the TH-MYCN mouse model with no related adverse effect." (PMID 38069407, 2023). "Furthermore, in vivo experiments confirmed that BMSC‐secreted exosomes‐loaded miR‐30b‐5p suppressed EZH2/PI3K/AKT axis to enhance apoptosis and inhibit tumour growth in nude mice." (PMID 37698037, 2023). "The oncogenic effect of EZH2 was further validated in vivo using OVCAR8 cells harboring the same system; downregulation of EZH2 expression following doxycycline treatment significantly inhibited xenograft tumor growth." (PMID 37210576, 2023). "The expression of EZH2, the major subunit of the PRC2 complex, in both tumor and immune cells can induce epigenetic and transcriptomic changes, which mobilize various elements of the TME and promote the development of solid tumors with immunosuppressive activity." (PMID 37909018, 2023). "Indeed, EZH2 inhibition by EPZ-6438 induced apoptosis in SMARCB1-mutant MRT cells and dose-dependent tumor regression in xenograft-bearing mice." (PMID 36900330, 2023).
tumor (continued). "In ovarian tumors, EZH2 expression was negatively correlated with intratumoral CD8+ T cells, and its expression inhibited the production of CXCL9 and CXCL10, thereby affecting CD8+ T cell infiltration within the tumor." (PMID 37909018, 2023). "Cytotoxicity experiments showed that the combination of DOX and EZH2 siRNA had a synergistic inhibitory effect on TNBC cells, and the nanomedicine showed excellent safety after systemic delivery due to the system’s favorable tumor-targeting ability." (PMID 38047286, 2023). "The most studied inhibitor of EZH2 is 3-deazanoplanocin A (DZNep), with numerous studies demonstrating its ability to decrease GBM cell self-renewal and viability in vitro and decrease tumor growth in vivo." (PMID 37205197, 2023). "Here, we demonstrate that targeting EZH2 using CRISPR/Cas9 or EPZ6438 results in significant antitumor effects in ATC cells, including reduced cell proliferation, colony formation, invasion and migration in vitro, as well as reduced tumor growth in vivo." (PMID 37175580, 2023). "In addition to activating EZH2 expression, MUC1-C binds directly to EZH2 and promotes H3K27 methylation with repression of tumor suppressor genes." (PMID 37821650, 2023). "KLF2 acts as tumor suppressor in NSCLC cells and its’ expression could be repressed through XIST via recruiting EZH2 to its promoter region." (PMID 37807067, 2023). "For example, we recently developed an EZH2 PROTAC degrader, which effectively targeted both canonical and noncanonical functions of EZH2, resulting in far superior tumor suppressive effects compared to catalytic inhibitors of EZH2." (PMID 36737841, 2023). "Therefore, we set out to identify an EZH2 inhibitor-based drug combination that was capable of killing CRPC and inducing frank tumor regression." (PMID 37104245, 2023). "Furthermore, in silico analysis of the EZH2 and FBP1 mRNA expressions in human CCA samples revealed that the EZH2 mRNA expression was upregulated in tumor samples, whereas the FBP1 expression was downregulated." (PMID 36900361, 2023). "Previous studies have demonstrated that in the absence of ERβ expression, EZH2 functions as an oncogene, in part through co-activation of NFκB to drive tumor progression." (PMID 36926316, 2023). "CDK1, ECT2, EZH2, GJB2, GPR37, GPX2, and GPX8 mRNA expression was up-regulated in the tumor group (p < 0.001), whereas GPX3, HYAL1, and TLR4 mRNA expression was down-regulated in the tumor group (p < 0.001) compared with those in the normal group." (PMID 37689745, 2023). "Additionally, miR-124a also acts as a tumor suppressor of UM, as it inhibits cell growth, migration, and invasion by affecting multiple targets such as CDK4, CDK6, cyclin D2 and enhancer of zeste homolog 2 (EZH2)." (PMID 37628989, 2023). "It has been reported that EZH2 can be used as a catalytic subunit of PRC2, the complex that participates in the transcriptional inhibition of multiple target genes, including the inactivation of more than 200 tumor suppressor genes." (PMID 36672374, 2023). "Together, our data demonstrate that VSV∆51-amiR-4-infected cells induce a bystander effect in the TME by secreting amiR-4-containing SEVs which facilitate tumour cell death via a synthetic lethal interaction between ARID1A and EZH2 with the addition of the small-molecule inhibitor GSK126." (PMID 35393414, 2022). "This study demonstrated that tumor cells with high EZH2 expression were not sensitive to PARPi treatment, and in patient-derived xenografts, EZH2 inhibitors sensitize CARM1-high OCs to PARPi." (PMID 36091750, 2022). "According to our data set, three genes, EZH2, GRPEL2, and NDRG1, and one clinical factor, tumor size, could be used as reliable indicators for evaluating the prognosis in patients with HCC." (PMID 36686830, 2022). "According to the HPA database, the increased staining intensity of the EZH2 protein level was detected in tumour tissues compared with noncarcinoma tissues." (PMID 35659256, 2022).